MUC19 (mucin 19, oligomeric (gene/pseudogene))
Description:
May function in ocular mucus homeostasis.
Synonyms: MUC-19; FLJ35746
Gene: Protein-coding gene on chromosome 12 (40,393,395 to 40,570,832, forward strand). Ensembl gene ENSG00000205592.
Subcellular location: Secreted
Genetic constraint (gnomAD): Missense variants: 4,113 observed, 4,645.1 expected, observed/expected ratio (o/e) 0.89, 90% interval 0.86 to 0.91. Synonymous variants: 1,374 observed, 1,574.6 expected, observed/expected ratio (o/e) 0.87, 90% interval 0.83 to 0.91.
Homologues: Orthologues: rat Muc19 (28% identical), mouse Muc19 (27% identical), tropical clawed frog otogl2 (7% identical). Paralogues in human: MUC5B (9% identical), MUC5AC (9% identical), MUC6 (7% identical), MUC2 (5% identical), OTOG (5% identical), VWF (5% identical), OTOGL (5% identical), FCGBP (4% identical), TECTA (4% identical), ZAN (3% identical), KCP (3% identical), CRIM1 (2% identical), and 7 more.
Diseases named in the same sentence as MUC19 in open-access papers:
MUC19 is named in the same sentence as 46 diseases in open-access papers, as found by Europe PMC text mining. Sharing a sentence is not in itself a finding about the gene and the disease. The quoted sentences say what the papers report.
breast carcinoma (9 papers, 2017 to 2024). "Further exploration of the mechanism of circ_0007534 regulation of cell proliferation revealed that upregulation of circ_0007534 promoted breast cancer cell proliferation and invasion through MUC19 by downregulating the expression of miR-593." (PMID 36505874, 2022). "It has been reported that MUC19 expression is involved in the pathogenesis of Sjogren syndrome and breast cancer; and breast cancer patients with higher MUC19 expression exhibited worse prognosis." (PMID 33828970, 2021). "In our research, we found that circ_0001982 promoted breast cancer progression through mediating miR-1287-5p/MUC19 pathway." (PMID 34082777, 2021). "Besides MUC16, other members of the mucin family, including MUC19 and MUC1 have been implicated in the glucose metabolism of different cancers, including breast cancer, bladder cancer, and endometrial carcinoma." (PMID 39219440, 2024). "MUC19 reportedly modulates proliferation, invasion and metastatic potential of breast cancer." (PMID 35672711, 2022). "Also, LIPF and MUC19, the gene that expresses SMGC, was associated with a worse survival probability in patients with breast cancer." (PMID 35798767, 2022). "Dysregulation of MUC19 was found to be strongly correlated with the progression of breast cancer." (PMID 34082777, 2021). "A previous study disclosed that MUC19 level was elevated in breast cancer." (PMID 34082777, 2021). "Lastly, despite many cancers observed not to harbor mutations in MUC12 and MUC19, breast cancer appears to have a unique profile." (PMID 28978023, 2017).
Crohn disease (8 papers, 2009 to 2024). A gastrointestinal disorder characterized by chronic inflammation involving all layers of the intestinal wall, noncaseating granulomas affecting the intestinal wall and regional lymph nodes, and transmural fibrosis. "Variants in both MUC19 and LRRK2 have been reported together in multiple GWAS investigating Crohn’s disease, ankylosing spondylitis, and autoimmune thyroid disease." (PMID 30861027, 2019). "Gene‐gene interaction analysis revealed significant interactions between MST1 and other susceptibility genes, including NOD2, MUC19 and ATG16L1 in contributing to Crohn's disease risk." (PMID 29441677, 2018). "Another noteworthy observation is that VDR was centred by MUC19, MST1, ATG16L1 and NOD2, which synergistically contributed to Crohn's disease risk." (PMID 29441677, 2018). "It is not clear at the LRRK2/MUC19 locus which is the key associated gene with Crohn's disease, although a recent study suggests that LRRK2 is the more likely to be truly disease-associated." (PMID 21152001, 2010). "While the association with MUC19 rs2933353 was not significant, given that MUC19 is a salivary mucin that plays a role in pathogen clearance in the oral cavity and SNPs in this gene are associated with Crohn’s disease, further validation of this association in a larger cohort would be required." (PMID 30558669, 2018). "We tested whether genes associated with Crohn's disease are also associated with ankylosing spondylitis and confirmed that the two diseases share associations at chromosome 1q32 near KIF21B, STAT3, IL12B, CDKAL1, LRRK2/MUC19, and chromosome 13q14." (PMID 21152001, 2010). "This study of genes associated with Crohn's disease has identified definite genome-wide significant association with AS of SNPs at chromosome 1q32 near KIF21B, and experiment-wise association at five other novel-AS loci including STAT3, IL12B, CDKAL1, LRRK2/MUC19, and at chr13q14." (PMID 21152001, 2010). "The co‐involvement of NOD2, JAK2, MUC19 and MST1 in mucosal defence and inflammation in Crohn's disease therefore deserves further study." (PMID 29441677, 2018).
colitis (3 papers, 2010 to 2021). Inflammation of the colon. "Genetic association studies suggest that LRRK2/MUC19 and ATG7 deficiency aggravates intestinal inflammation in mouse models of colitis." (PMID 33904657, 2021). "Furthermore, genetic association studies have suggested that LRRK2/MUC19 and ATG7 deficiency aggravate intestinal inflammation in a mouse model of colitis." (PMID 30669622, 2019).
colorectal cancer (3 papers, 2021 to 2024). A primary or metastatic malignant neoplasm that affects the colon or rectum. "Chu’s study also reported that MUC19 mutations can be detected in the case of colorectal cancer, similar to the sigmoid colon cancer patient of our study." (PMID 39830210, 2024). "However, there are limited studies regarding the relationship between MUC19 mutation and colorectal cancer." (PMID 39830210, 2024). "MUC19, which encodes Mucin‐19, is linked with inflammatory response, hematopoietic progenitor and salivary gland cell differentiation through mice studies, and is associated with TN Polyagglutination Syndrome and colorectal cancer." (PMID 33778321, 2021). "MUC19 is a secreted mucin that has been limitedly researched with regard to colorectal cancer." (PMID 36900282, 2023).
inflammatory bowel disease (3 papers, 2021 to 2022). A spectrum of small and large bowel inflammatory diseases of unknown etiology. "In addition, MUC19 mutation was found in inflammatory bowel disease, melanoma, colorectal adenocarcinoma, and esophageal squamous cell carcinoma." (PMID 33828970, 2021).
lung carcinoma (3 papers, 2021 to 2023). "More importantly, we validated our results in the MSKCC cohort containing 75 American lung cancer patients receiving immunotherapy and with MUC19 mutation information." (PMID 33828970, 2021). "Therefore, we further estimated the association between these mutations and the efficacy of immunotherapy in a published lung cancer dataset, and the results demonstrated that MUC19 and PCDHB5- mutations were related with favorable results of immunotherapy." (PMID 36389707, 2022). "Using the cBioPortal website, we downloaded all lung cancer datasets containing MUC19 mutations." (PMID 33828970, 2021). "We found that the mutation rate of MUC19 in lung cancer was higher in Asian patients than in non-Asian patients (LUSC-KR 63.53% vs. LUSC-US 5.15%; LUSC-US 5.15% vs. LUAD-US 1.16%)." (PMID 33828970, 2021). "At present, what we understand regarding MUC19 is limited, and the role of MUC19 in lung cancer also remains unclear." (PMID 33828970, 2021). "This is the first study to explore and uncover the role of MUC19 in lung cancer." (PMID 33828970, 2021).
melanoma (3 papers, 2013 to 2021). A malignant, usually aggressive tumor composed of atypical, neoplastic melanocytes. "MUC19, PAICS, RBMXL1, KIF23 have been identified in melanoma, which might deserve further investigations the role in cancer." (PMID 28159935, 2017). "We also identified mutations in four genes (MUC19, PAICS, RBMXL1, KIF23) never reported in melanoma, which might deserve further investigations." (PMID 23704925, 2013).
Sjögren syndrome (3 papers, 2014 to 2021). "Gel-forming mucin MUC5AC and MUC19 decline in Sjögren’s syndrome and other types of dry eye, MUC5AC was also suppressed in several dry eye animal models." (PMID 24498087, 2014). "MUC19 has been found in patients with Sjögren syndrome and in middle ear epithelium." (PMID 32899224, 2020).
Allergy (1 paper, 2020). An allergy is an immune response or reaction to substances that are usually not harmful. "Moreover, murine Muc19 has been reported in mouse models of allergy and of mucous cell deficiency within salivary glands." (PMID 32899224, 2020).
autism (1 paper, 2020). Persistent deficits in social interaction and communication and interaction as well as a markedly restricted repertoire of activity and interest as well as repetitive patterns of behavior. "This observed expression pattern indeed shows that MUC19 is highly unlikely to be the causative gene for intellectual disability and autism." (PMID 31963867, 2020). "Patient DGDP289A displays developmental delays, autism, impaired motor skills and craniofacial anomalies and has a ~328 kb minimal microdeletion at 12q12, encompassing LRRK2 and MUC19." (PMID 31963867, 2020).
bacterial pneumonia (1 paper, 2024). Acute infection of the lung parenchyma caused by bacteria (e.g., Streptococcus pneumoniae, Haemophilus influenzae, Chlamydia pneumoniae, Mycoplasma pneumoniae, and Legionella pneumophila). "Furthermore, the revealed mechanism of the METTL3/NEAT1/CTCF/MUC19 axis provides new theoretical knowledge for bacterial pneumonia treatment and furnishes evidence for future therapeutic direction." (PMID 38757482, 2024).
Cognitive impairment (1 paper, 2020). Abnormal cognition is characterized by deficits in thinking, reasoning, or remembering. "To further support our hypothesis that LRRK2 is a candidate gene for cognitive impairment, we examined the transcript levels of both LRRK2 and MUC19 in human tissues." (PMID 31963867, 2020).
lymph node metastases (1 paper, 2024). "Moreover, HC-SMGs such as MUC19, MAN2A1 and HNRNPCL1 were exclusively mutated in rNEN-L patients with lymph node metastases, suggesting their involvement in the increasingly aggressive behavior of this disease." (PMID 39548061, 2024).
lymphoma (1 paper, 2025). A malignant (clonal) proliferation of B- lymphocytes or T- lymphocytes which involves the lymph nodes, bone marrow and/or extranodal sites. "In conclusion, these results provide novel insights into the roles of MUC19 in EBV latency, highlighting its potential as a promising therapeutic target for the treatment of EBV-associated lymphomas." (PMID 40996224, 2025).
metastatic melanoma (1 paper, 2024). A melanoma that has spread from its primary site to another anatomic site. "Six of these lncRNAs - AC068594.1, C7orf71, FAM41C, GPC5-AS1, MUC19, and LINC00402 - were correlated with survival time in metastatic melanoma patients." (PMID 39764216, 2024).
Parkinson disease (1 paper, 2024). A progressive degenerative disorder of the central nervous system characterized by loss of dopamine producing neurons in the substantia nigra and the presence of Lewy bodies in the substantia nigra and locus coeruleus. "The GWAS result revealed that there were significant associations between Parkinson's disease and eleven SNPs located within the gene body of MUC19, providing evidence for the relationship between MUC19 and Parkinson’s disease." (PMID 38350848, 2024).
rhinosinusitis (1 paper, 2015). "The present study further extends these findings by showing for the first time an increased MUC19-expression within a model system of bacteria-induced rhinosinusitis." (PMID 26207629, 2015). "Here, we could demonstrate a 1,8-cineol-dependent reduction of mucus-production and particularly MUC19 and MUC2 gene expression in ex vivo cultured human nasal slices in a novel model for experimental rhinosinusitis." (PMID 26207629, 2015).
viral infections (1 paper, 2025). "Similarly, MUC19 (Mucin 19) encodes a Mucin family protein that has been involved in the immune response to parasitic and viral infections." (PMID 40070201, 2025).
xerostomia (1 paper, 2012). Dryness of the mouth resulting from reduced salivary secretion. "Muc19 was down-regulated twofold 12 weeks post-IR, which might cause the saliva to lose its lubricating and protective properties, and contribute to the xerostomia seen in irradiated patients." (PMID 22792391, 2012).
cancer (8 papers, 2017 to 2024). A tumor composed of atypical neoplastic, often pleomorphic cells that invade other tissues. "Future studies should aim to characterize the role of MUC19 mutation in mediating cancer immune responses, and large-scale prospective studies will be required to validate our results." (PMID 33828970, 2021). "Hypoxia upregulates circ0001982, which sponges off miR-1287-5p from its target mucin 19 (MUC19) and promotes cancer cell growth, invasion, and migration through elevated glycolysis in vitro and in vivo." (PMID 37583933, 2023).
infection (4 papers, 2019 to 2025). The state of being infected such as from the introduction of a foreign agent such as serum, vaccine, antigenic substance or organism. "For instance, the membrane-tethered MUC12 exhibited a similar expression pattern to MUC19 after EBV primary infection." (PMID 40996224, 2025). "The results showed that MUC19 expression was upregulated in EBV-infected B cells 14 days post-infection." (PMID 40996224, 2025). "BALB/c mice were infected with HMPV, and the expression of Muc1, Muc2, Muc4, Muc5ac, Muc5b, Muc15, Muc16, Muc19, and Muc20 were analyzed at 12, 24 and 48 h after infection." (PMID 32899224, 2020). "In order to explore the effect of Muc19 on host immune responses at a later time of infection, lung cellular infiltration was also analyzed at day 7 after infection, when T-cell recruitment is increased in the lungs of HMPV-infected mice." (PMID 32899224, 2020). "Besides MUC19, there are other interesting CNVs shown from our primary infection model, including IRF4/DUSP22 duplication and Notch homolog 2 N-terminal-like protein A (NOTCH2NLA) deletion." (PMID 40996224, 2025). "This work demonstrates that not only is Muc19 expressed in the lungs of infected mice, but it also contributes to HMPV-induced pathogenesis and infection." (PMID 32899224, 2020). "Moreover, we observed that the absence of Muc19 led to a modest, yet significant, reduction in lung titers at day 3 after infection." (PMID 32899224, 2020). "Compared to uninfected cells, HMPV infection induced a significant fold-increase expression of MUC1 (8.3 ± 2), MUC2 (43.4 ± 13), MUC4 (54 ± 12), MUC5ac (23.3 ± 11.5) and MUC19 (77 ± 35), while no significant induction of MUC15, MUC16 and MUC20 was observed." (PMID 32899224, 2020).
tumor (4 papers, 2020 to 2023). "We observed a decrease in the expression of genes encoding membrane-bound MUC15 and secreted MUC7 and MUC19 in tumor samples (p < 0.01)." (PMID 33182511, 2020). "In addition, circ_0001982 silencing reduced xenograft tumor growth by regulating miR-1287-5p/MUC19 axis." (PMID 34082777, 2021). "A recent study showed the overexpression of MUC1, MUC19, MUC4, MUC5AC, and MUC5B in the mucinous metaplasia of tissues isolated from Pten conditional knockout mice and human PCa tumor tissues." (PMID 36980526, 2023). "However, amongst CRC lung metastasis samples, MUC19 mutations have been identified that are not present in the primary tumor, thus suggesting a role played by MUC19 concerning distant spread." (PMID 36900282, 2023).
bacterial infection (1 paper, 2021). "More interestingly, bacterial infection (Streptococcus pneumoniae, nontypeable Haemophilus influenzae) upregulated MUC19 expression." (PMID 33828970, 2021).
MUC19 also shares sentences with these, for which no sentence is quoted: ankylosing spondylitis (1 paper); asthma (1); autoimmune thyroid disease (1); bladder cancer (1); chronic otitis media (1); colorectal adenocarcinoma (1); dental caries (1); developmental delays (1); dry eye (1); endometrial carcinoma (1); endothelial dysfunction (1); esophageal squamous cell carcinoma (1); inflammation (1); Intellectual disability (1); invasive carcinoma (1); malignant brain tumors (1); metastasis (1); non-small cell lung carcinoma (1); ovarian clear cell cancer (1); psoriasis (1); pulmonary fibrosis (1); sigmoid colon cancer (1); ulcerative colitis (1).